AMBRA1 (autophagy and beclin 1 regulator 1)
Diseases named in the same sentence as AMBRA1 in open-access papers (continued):
Sharing a sentence is not in itself a finding about the gene and the disease.
autism (continued). "Research on AMBRA1 heterozygous mice reveals that they display behaviors similar to autism, including repetitive actions, cognitive inflexibility, and impaired social interactions." (PMID 40076836, 2025). "For example, several studies have demonstrated that WDFY3, AMBRA1, and PARK2 gene mutations manifest as autism-like symptoms and as mitophagy dysfunction." (PMID 37108406, 2023). "Individual z-standardized values for single readouts of the autism composite score of female Ambra1+/+ and Ambra1+/−mice." (PMID 24904333, 2014). "Individual z-standardized values for single readouts of the autism composite score of male Ambra1+/+ and Ambra1+/−mice." (PMID 24904333, 2014). "Based on these typical behavioral symptoms, we calculated for Ambra1+/− mice an autism severity composite score, as it had originally been developed for autism severity estimation in Nlgn4−/− mice." (PMID 24904333, 2014). "Given the paucity of data relating to female autism, we exploit the Ambra1+/− female model to investigate whether rectifying the inhibitory input onto hippocampal principal neurons (PN) rescues their ASD-like phenotype at both the systems and circuits level." (PMID 36804922, 2023). "Given that schizophrenia has been characterized by reduced mTOR activation and increased synaptic pruning, it might be expected to show a different pattern from that of autism with regard to AMBRA1 expression, activity, and direction of effects." (PMID 31687209, 2019). "Moreover, they suggest Ambra1 heterozygous mice as a novel multifaceted and construct-valid genetic mouse model for female autism." (PMID 28994820, 2017). "However, significance of AMBRA1 for autistic phenotypes in humans and, apart from behavior, for other autism-typical features, namely early brain enlargement or increased seizure propensity, has remained unexplored." (PMID 28994820, 2017). "We note that Ambra1+/− mice are the first autism model showing autism-typical brain enlargement." (PMID 28994820, 2017). "Together, these data support Ambra1+/−mice as multidimensional model of human autism." (PMID 28994820, 2017). "Even then, it will remain to be determined if autophagy-related mechanisms can be efficiently influenced by non-toxic pharmacological tools such that a permanent rescue from the autism-like symptoms in female Ambra1+/− mice will ensue and open ways for later application in human ASD." (PMID 24904333, 2014). "As a first clue to why females might be more severely affected by autism-like features, we detected a more pronounced reduction in Ambra1 protein from WT level in females as compared to males." (PMID 24904333, 2014). "Together, the results of autism-like phenotype testing are in line with the observation of a marked female autistic phenotype in Ambra1+/− mice, and only mild subthreshold autistic symptoms (nesting score, social memory) in male Ambra1+/− mice." (PMID 24904333, 2014). "Surprisingly, comprehensive behavioral characterization of these mice revealed an autism-like phenotype in Ambra1+/− females only, including compromised communication and social interactions, a tendency of enhanced stereotypies/repetitive behaviors, and impaired cognitive flexibility." (PMID 24904333, 2014). "Indeed, we show here that Ambra1+/− mice display autism-like symptoms, including social interaction and communication deficits, repetitive behaviors, and cognitive rigidity." (PMID 24904333, 2014). "Partial loss-of-function, reflected by a relative decrease in AMBRA1 mRNA levels in PBMC of female risk genotype (AA) carriers, may suggest an underlying autism-causing mechanism similar to that in heterozygous mice where Ambra1 reduction was stronger in female than male mutant cortex." (PMID 28994820, 2017).
autism (continued). "This trait is quantifiable by the autism severity composite score, which even allows a behavior-based genotype predictability of >90%.29, 34 As first mechanistic hint explaining the prominent gender difference, stronger reduction of Ambra1 protein in the cortex of Ambra1+/− females was found." (PMID 28994820, 2017). "Since autism is usually diagnosed in children before the age of 3 years, assessment of neurobehavioral developmental milestones and early ultrasound communication in neonatal mice up to the age of 3–4 weeks has been important for further characterization of the Ambra1+/− mouse model of autism." (PMID 24904333, 2014). "Searching for further autism-relevant characteristics in Ambra1+/− mice, we observe reduced interest of female but not male mutants regarding pheromone signals of the respective other gender in the social intellicage set-up." (PMID 28994820, 2017).
schizophrenia (7 papers, 2014 to 2024). A major psychotic disorder characterized by abnormalities in the perception or expression of reality. "In line with the importance of Ambra1 for normal brain development, a genome-wide association study on schizophrenia patients identified a genetic risk variation in a region on chromosome 11 (11p11.2) containing the AMBRA1 gene." (PMID 29488136, 2018). "Despite its implications in both schizophrenia and ASDs, the underlying neurophysiological mechanism linking Ambra1 loss to these pathologies is unknown." (PMID 29488136, 2018). "Interestingly, a recent genome-wide association study on schizophrenia identified a genetic risk variation in a region on chromosome 11 (11p11.2) containing AMBRA1." (PMID 24904333, 2014). "Chromosome 11p11 also harbours genes that have been previously associated with schizophrenia and/or brain structural phenotypes, including CHRM4, MDK, AMBRA1 and HARBI127,66,67." (PMID 38016951, 2023). "Different SNPs of AMBRA1 have also been linked with risk of schizophrenia, although sex differences were not investigated here." (PMID 31687209, 2019). "However, any potential role of Ambra1 mutations in the expression of a complex behavioral phenotype reminiscent of schizophrenia or ASD as classical neurodevelopmental disorders has not been explored yet." (PMID 24904333, 2014). "Expression of the ‘Macroautophagy’ genes AMBRA1, PRKAB1, TUBA1A, TUBB2A, and TUBA4A was restored in the AT-schizophrenia group." (PMID 38648100, 2024).
medulloblastoma (5 papers, 2021 to 2023). A malignant, invasive embryonal neoplasm arising from the cerebellum. "The pro-autophagy factor AMBRA1 can regulate both the growth and proliferation of medulloblastoma stem cells through stimulating the c-MYC/AMBRA1/STAT3 axis." (PMID 37422448, 2023). "Knockdown of the pro-autophagy factor AMBRA1 in medulloblastoma, a powerful oncogenic signaling pathway, can reduce medulloblastoma stem cell growth and migration." (PMID 37422448, 2023). "In another study, the role of the pro-autophagy factor AMBRA1 in regulating medulloblastoma was identified showing that AMBRA1 expression depends on c-MYC levels and is correlated with poor prognosis in group 3 patients." (PMID 36197606, 2022). "Knockdown of AMBRA1 reduced the stemness, growth, and invasiveness of group 3 medulloblastoma stem cells." (PMID 36197606, 2022). "A recent study has shown a relationship among AMBRA1, CUL4–DDB1 complex, and STAT3 in medulloblastoma (MB) stem cells, demonstrating that AMBRA1, through its direct interaction with the CUL4–DDB1 complex, is involved in the degradation of SOCS3, an inhibitor of STAT3 activity." (PMID 37106439, 2023). "However, another study presented a different perspective that AMBRA1 is a tumor stemness-promoting factor in medulloblastoma (MB)." (PMID 36237336, 2022).
colorectal cancer (4 papers, 2014 to 2022). A primary or metastatic malignant neoplasm that affects the colon or rectum. "We determined that serum deprivation-induced autophagy was associated with Ambra1 upregulation in colorectal cancer cell lines." (PMID 24587252, 2014). "Our novel findings suggested that Ambra1 not only promoted autophagy in this colorectal cancer cell line but also had the ability to control the switch between autophagy and apoptosis in these cells, thereby altering cellular fate." (PMID 24587252, 2014). "Therefore, we concluded that AMBRA1 negatively modulates the stemness of colorectal cancer cells via the ALDH1B1-β–catenin axis." (PMID 34769507, 2021). "As AMBRA1 affected CTNNB1 transcription via ALDH1B1, which is a crucial CSC marker of colorectal cancer, we next investigated whether AMBRA1 expression affects the mRNA levels of several CSC-related β-catenin target genes, including LGR5, HIF1a, ALDH1A3, CD24, and SOX4." (PMID 34769507, 2021). "However, whether Ambra1 plays an important role in the autophagy pathway in colorectal cancer cells is unknown." (PMID 24587252, 2014). "In this study, we examined the role of Ambra1 in autophagy and apoptosis in SW620 colorectal cancer cells." (PMID 24587252, 2014). "Inhibition of EZH2, using siRNA or EZH2i DZNep, in colorectal cancer cells (RKO and HCT116), also increased LC3B-II levels and the expression of the ATG-related protein AMBRA1 (autophagy and BECLIN-1 regulator 1) and favored apoptosis but inhibited cell proliferation and migration." (PMID 31861179, 2019).
ischemia (4 papers, 2018 to 2023). A hypoperfusion of the BLOOD through an organ or tissue caused by a PATHOLOGIC CONSTRICTION or obstruction of its BLOOD VESSELS, or an absence of BLOOD CIRCULATION. "Old autophagy-impaired-AMBRA1 mice show higher RGC susceptibility, and heterozygous ablation of AMBRA1 leads to a remarkable reduction in RGC survivability after ischemia." (PMID 37566048, 2023). "Heterozygous ablation of Ambra1 resulted in a significant reduction of RGC survival following ischemia (12.0 ± 1.2%), suggesting that partial genetic impairment of basal autophagy depletes RGCs from a relevant endogenous neuroprotective mechanism." (PMID 30250019, 2018). "Following the evidence on AMBRA1-mediated mitophagy in relay with HUWE1 and IKKα, we checked the physiopathological relevance of this functional interplay in models of ischaemia." (PMID 30217973, 2018).
lung carcinoma (4 papers, 2020 to 2025). "In lung cancer, loss of AMBRA1 promoted growth of mice lung adenocarcinoma (LUAD), and low levels of AMBRA1 are correlated with LUAD patients' poorer survival." (PMID 40464146, 2025). "Our study found that in DLBCL, miR-7-5p prevented MYC dephosphorylation through AMBRA1 downregulation, which is consistent with the lung cancer research." (PMID 38393538, 2025). "In most lung cancer cell lines, low expression levels of AMBRA1 and high expression levels of phosphorylated MYC have been reported." (PMID 38393538, 2025). "In this study, the function and regulatory mechanisms of AMBRA1 were explored in the progression of non‐small cell lung cancer (NSCLC)." (PMID 40464146, 2025). "Similarly, MIR7-3HG upregulation in our analysis contrasts a report showing that MIR7-3HG downregulates the tumor suppressor AMBRA1 and prevents MYC dephosphorylation in lung cancer." (PMID 32260415, 2020).
cholangiocarcinoma (3 papers, 2017 to 2024). A carcinoma that arises from the intrahepatic biliary tree (intrahepatic cholangiocarcinoma) or from the junction, or adjacent to the junction, of the right and left hepatic ducts (hilar cholangiocarcinoma). "However, another study implied that Ambra1 may have tumour-promoting functions, since Ambra1 overexpression correlated with invasion and poor survival in cholangiocarcinoma." (PMID 28362576, 2017).
colon cancer (3 papers, 2014 to 2024). "Beclin1 also acts as a tumor promoter in colon cancer, and a previous study suggested that Ambra1 regulates autophagy during murine embryogenesis by activating Beclin1." (PMID 24587252, 2014). "Additionally, for LoVo colon cancer cells, irinotecan inhibits mTOR and activates the autophagy-related genes, ULK1, ATG13, ATG4L, and AMBRA1, promoting autophagy with increased numbers of lysosomes and lysosomal activity, which contribute to irinotecan resistance." (PMID 39456585, 2024).
diabetes (3 papers, 2018 to 2025). "Taken together, our results show that autophagy deficiency can “host” prediabetes and that the dysmetabolic profile of Ambra1 mice fits well with the early stage of clinical diabetes." (PMID 30532260, 2018). "Our findings demonstrated that Ambra1 loss enhanced Müller glial cell proliferation while markedly reducing diabetes-related retinal inflammation, notably without triggering gliotic changes." (PMID 41001311, 2025). "Finally, the ability of CR to rebalance the alterations of ACCs as possible markers of incomplete long-chain FAO in Ambra1 mice reveals the complex relationship among autophagy, dietary factors, dysfunction of lipid and glucose metabolism and diabetes." (PMID 30532260, 2018). "Our findings on the association between genetic variants in AMBRA1, ATG13 and ATG16L1 and proinsulin levels are in agreement with previous evidence reporting autophagy deficiency as an important determinant in the pathogenesis of insulin resistance and diabetes." (PMID 30908504, 2019). "Retinal sections from four groups, including Ambra1 knockout and control mice, with and without STZ-induced diabetes, were subjected to immunohistochemical analysis." (PMID 41001311, 2025).
glioma (3 papers, 2021). A benign or malignant brain and spinal cord tumor that arises from glial cells (astrocytes, oligodendrocytes, ependymal cells). "Altogether, these findings open a novel scenario for targeting c-MYC transcription, and it would be of the highest importance to check whether such an AMBRA1 dependence could be detected in other different c-MYC-driven tumours, such as leukaemia or gliomas." (PMID 34302498, 2021).
lung adenocarcinoma (3 papers, 2023 to 2025). A carcinoma that arises from the lung and is characterized by the presence of malignant glandular epithelial cells. "Ambra1 deletion not only promotes lung adenocarcinoma growth, but a low level of Ambra1 is associated with poorer prognosis in lung adenocarcinoma patients." (PMID 37225761, 2023).
squamous cell carcinoma (3 papers, 2017 to 2022). A carcinoma arising from squamous epithelial cells. "We therefore investigated the role of Ambra1 in tumour-associated phenotypes regulated by the Src/FAK pathway in squamous cell carcinoma (SCC) cells derived from the DMBA/TPA model of carcinogenesis (driven by mutated oncogenic H-Ras)." (PMID 28362576, 2017). "Here, using mouse squamous cell carcinoma cells, we report a completely new function for the autophagy protein Ambra1 as the first described ‘spatial rheostat’ controlling the Src/FAK pathway." (PMID 28362576, 2017). "Recently, it has been demonstrated that AMBRA1 controls the focal adhesion kinase 1 (FAK1)-mediated signaling pathway by interacting with FAK1 and SRC ﻿in mouse squamous cell carcinoma cells." (PMID 33953176, 2021).
age-related macular degeneration (2 papers, 2020 to 2023). Age-related loss of vision in the central portion of the retina (macula), secondary to retinal degeneration. "Additionally, crystallins can also be linked to age related macular degeneration, and altered crystallins lead to impaired lysosomal clearance in the retinal pigment epithelium, however they have not been linked to AMBRA1 so far." (PMID 32337073, 2020).
Cowden syndrome (2 papers, 2022 to 2025). "We had identified a missense mutation in AMBRA1 through exome analysis of a family with Cowden syndrome." (PMID 40734673, 2025). "While mutations in PTEN were identified as the cause of Cowden syndrome, we have recently identified missense mutations in AMBRA1 by exome analysis of the family of a Cowden syndrome patient without a PTEN mutation." (PMID 40734673, 2025). "We first confirmed that the Cowden syndrome patient-type AMBRA1 mutant attenuated the function of controlling the stability of cyclin D and cell proliferation arrest." (PMID 40734673, 2025). "We had identified a missense mutation in AMBRA1 by exome analysis of the family of the patient with Cowden syndrome who had multiple neoplasms without Phosphatase and tensin homolog (PTEN) mutations." (PMID 40734673, 2025). "In this study, we demonstrated that AMBRA1 depletion induced hyperproliferation of cells by disrupting primary cilia and could possibly be a novel candidate of Cowden syndrome." (PMID 36232425, 2022).
hepatocellular carcinoma (2 papers, 2022 to 2025). A malignant tumor that arises from hepatocytes. "In studies employing hepatocytes and hepatocellular carcinoma cells, the inhibition of mitophagy has been shown to increase fat droplet deposition, as indicated by the altered expression patterns of mitophagy indicators such as AMBRA1, Parkin, and PINK1." (PMID 40141351, 2025).
neuropathy (2 papers, 2018 to 2025). A disorder affecting the nervous system that manifests with pain, tingling, numbness, and/or muscle weakness. "This mirrors a caloric restriction (CR)-like state, previously associated with improved neuropathy recovery and autophagy activation in wild-type and Ambra1+/gt mice." (PMID 41158618, 2025). "Hence, we hypothesized that prediabetes in Ambra1 mice may be a possible causal factor in the exacerbation of CCI-induced neuropathy and chronic pain and that by increasing autophagy we could totally or partially relieve the neuropathic condition." (PMID 30532260, 2018). "We found that CR ameliorates neuropathy throughout anti-inflammatory and metabolic mechanisms both in Ambra1 and in WT animals subjected to nerve injury." (PMID 30532260, 2018). "In Ambra1 mice, neuropathy induced an increase of different ACCs such as short-chain, odd-chain, 3-hydroxy and dicarboxy and medium and long-chain ACCs, as well as an increase of aromatic AA Tyr, BCAAs and direct products of BCAA catabolism." (PMID 30532260, 2018). "We previously demonstrated that Ambra1 mice subjected to CCI never recovered from neuropathy, as here confirmed." (PMID 30532260, 2018).
prostate adenocarcinoma (2 papers, 2015 to 2021). "The subcellular localization and expression of AMBRA1 and SQSTM1 proteins were observed and scored by IHC on large section of prostate adenocarcinoma from 26 patients." (PMID 26423274, 2015).
retinal degeneration (2 papers, 2023 to 2025). Degeneration of the retina. "In this study we show that a moderate reduction in autophagy, achieved through monoallelic deletion of Ambra1 (Ambra1+/gt mice), exacerbates the retinal degeneration and visual function impairment associated with the aging process." (PMID 35875981, 2023). "In Ambra1+/gt mice, alterations in proteostasis within RPE result in RPE atrophy, increased lipid peroxidation, metabolic dysfunction, and lipofuscin formation later, and a heightened susceptibility to aged-associated retinal degeneration." (PMID 41288322, 2025). "However, when autophagy is defective, as in Ambra1+/gt mice, the retina cannot appropriately respond to starvation by activating autophagy, thus resulting in retinal degeneration and vision defects in the long term." (PMID 35875981, 2023). "Given the retinal phenotype observed in Ambra1+/gt mice, and the fact that SI exerts a time- and region-dependent effect, this finding demonstrates increased susceptibility of the Ambra1+/gt RPE to stress, resulting in exacerbated retinal degeneration." (PMID 35875981, 2023). "Moreover, Ambra1+/gt mice were more prone to retinal degeneration after RPE stress." (PMID 35875981, 2023). "Overall, our study demonstrates that AMBRA1-mediated autophagy may be a key process for preventing age- and stress-dependent RPE dysfunction and retinal degeneration." (PMID 35875981, 2023).
Alzheimer disease (1 paper, 2025). A progressive, neurodegenerative disease characterized by loss of function and death of nerve cells in several areas of the brain leading to loss of cognitive function such as memory and language. "It provides a focused analysis of the specific functions and activation mechanisms of key receptors—including BNIP3, NIX, FUNDC1, and AMBRA1—in models of Alzheimer’s disease, Parkinson’s disease, and amyotrophic lateral sclerosis." (PMID 41341510, 2025).